USP14 (ubiquitin specific peptidase 14)
Diseases named in the same sentence as USP14 in open-access papers (continued):
Sharing a sentence is not in itself a finding about the gene and the disease.
melanoma (7 papers, 2019 to 2025). A malignant, usually aggressive tumor composed of atypical, neoplastic melanocytes. "At the molecular level, targeting USP14 in melanoma increases oxidative and proteotoxic stress and subsequently triggers ROS-dependent and caspase-independent cell death that overcomes resistance to BRAF inhibitors." (PMID 36694209, 2023). "The selective inhibitor b-AP15 also showed anti-melanoma activity in a mouse model of a BRAFi-resistant tumor, suggesting that USP14 is a possible target in melanoma with acquired resistance to targeted therapies." (PMID 33800394, 2021). "USP14 participates in the resistance to BRAF inhibitors in melanoma cells." (PMID 36694209, 2023). "Interestingly, the antitumor effect of USP14 targeting is applicable to BRAFV600E-, NRAS-, and NF1-mutated melanoma cells and to BRAF/MEK inhibitor-resistant cells." (PMID 35884430, 2022). "Increased activity of USP14, a proteasome-associated DUB, was observed in melanoma cells and in melanoma patients compared to normal skin and nevi b-AP15, a selective USP14 inhibitor; the USP14 reduced proliferation of melanoma cells independent of the mutational cell status." (PMID 33800394, 2021). "In addition, the DUB inhibitor VLX1570, which inhibits USP14 and UCHL5, has undergone phase 1 clinical trials in multiple melanoma patients." (PMID 37107644, 2023).
Parkinson disease (7 papers, 2012 to 2025). A progressive degenerative disorder of the central nervous system characterized by loss of dopamine producing neurons in the substantia nigra and the presence of Lewy bodies in the substantia nigra and locus coeruleus. "The absence or dysfunction of USP14 is associated with several neurodegenerative diseases, such as Alzheimer's and Parkinson's diseases, which are characterised by protein aggregation and neuronal damage." (PMID 40988122, 2025). "To monitor the therapeutic potential of USP14 inhibition in a mitophagy‐deficient background in vivo, we selected animal models of Parkinson's disease (PD), which are associated with mutations in the protein kinase PINK1 and E3 ubiquitin ligase Parkin, both key regulators of mitophagy." (PMID 30249595, 2018). "Ubiquitin specific protease-14 (USP14) is critical for controlling proteostasis disturbed in human disorders, including Parkinson's disease (PD)." (PMID 39916840, 2025). "Thus, inhibition of DUBs using inhibitors (e.g., IU1, a USP14 inhibitor) may yield beneficial effects against the progression of Parkinson's disease." (PMID 34089575, 2021). "Genetic or pharmacological inhibition of USP14 in vivo corrected mitochondrial dysfunction and locomotion behaviour of PINK1/Parkin mutant Drosophila model of Parkinson's disease, an age‐related progressive neurodegenerative disorder that is correlated with diminished mitochondrial quality control." (PMID 30249595, 2018).
Stroke (6 papers, 2015 to 2024). Sudden impairment of blood flow to a part of the brain due to occlusion or rupture of an artery to the brain. "M2 microglia-derived exosomal miR-124 can reduce neuronal apoptosis and relieve brain injury after stroke by downregulating ubiquitin-specific protease 14 (USP14)." (PMID 38433165, 2024). "miR-124 affects a plethora of signaling molecules such as the recently identified inhibition of deubiquitination of Usp14, significantly contributing to the reduction of post-stroke brain injury in rodents." (PMID 32361827, 2021). "Our results expand our understanding of the role of USP14 in stroke pathology." (PMID 37269080, 2023). "miR-124 targets USP14 to suppresses deubiquitination of REST, which contributes to reduced brain injury and functional impairment, enhanced neurovascular remodeling, and increased angioneurogenesis 8 weeks post-stroke in mice with MCAO." (PMID 26041995, 2015).
liver cancer (5 papers, 2022 to 2025). An epithelial or non-epithelial malignant neoplasm that arises from the liver. "Our investigation of TCGA database highlighted a strong correlation between USP14 and the prognosis of individuals diagnosed with liver cancer, where increased levels of USP14 were consistently linked to a worsened prognosis." (PMID 38383348, 2024). "In HCC, USP14 is highly expressed in liver cancer and is associated with a poor prognosis in patients with HCC." (PMID 35875077, 2022). "Our work not only revealed the important function of USP14 in the RT tolerance of liver cancer but also provided insights into the mechanism of radiation-driven ferroptosis defenses." (PMID 40595451, 2025). "This study serves as an experimental and theoretical foundation for understanding the development and mechanisms of USP14 in liver cancer as well as for the subsequent treatment of this disease." (PMID 38383348, 2024). "USP14 regulates the autophagy function of liver cancer cells by regulating the interaction between SQSTM1/P62 and HK2." (PMID 38383348, 2024). "To investigate the role of USP14 in regulating liver cancer, we conducted an experiment focusing on the interaction between USP14 and HK2." (PMID 38383348, 2024). "The results revealed that USP14 was expressed in both the nucleus and cytoplasm of liver cancer cells." (PMID 38383348, 2024). "Lactation of lysine has recently been identified in liver cancer, which occurs mainly on two tumor‐associated proteins, USP14 and ABCF1, which promote the development of liver cancer and lung metastasis." (PMID 39184862, 2024). "The study also explored the newly discovered interaction between USP14 and HK2 protein and further investigated how USP14 regulates the occurrence and development of liver cancer through HK2." (PMID 38383348, 2024). "Currently, there is a lack of research investigating the expression and regulatory mechanisms of USP14 in liver cancer, and its specific role and molecular mechanisms in the initiation and progression of liver cancer." (PMID 38383348, 2024). "The results demonstrated that the knockdown of USP14 resulted in decreased vitality, proliferation, migration, and invasion of liver cancer cells, while enhancing apoptosis." (PMID 38383348, 2024). "sh-USP14 was transfected into MHCC97H and HCCLM3 liver cancer cell lines, and western blotting was performed to measure the expression of USP14." (PMID 38383348, 2024). "The results obtained from CCK-8 and clone formation experiments provide substantial evidence indicating that the overexpression of USP14 hampers the growth of liver cancer cells." (PMID 38383348, 2024). "We found that sh-USP14 significantly inhibits the proliferation, invasion, and invasion of liver cancer cells, promoting apoptosis." (PMID 38383348, 2024). "Using bioinformatics analysis based on the Cancer Genome Atlas (TCGA) database, we screened and identified USP14 as highly expressed in liver cancer." (PMID 38383348, 2024). "In summary, these findings suggested that sh-USP14 effectively enhanced programmed cell death in liver cancer cells." (PMID 38383348, 2024). "IU1, an inhibitor of USP14, can significantly inhibit the proliferation of liver cancer cells and liver cancer tissue tumors." (PMID 35875077, 2022). "In the hypoxic environment of liver cancer, USP14 can enhance the transcriptional activity of HIF-1α and the stability of HIF-1α through deubiquitination, which in turn promotes the migration and invasion of HCC cells in a HIF-1α-dependent manner." (PMID 35875077, 2022). "Our results indicate that USP14 plays a crucial role in the carcinogenesis of liver cancer." (PMID 38383348, 2024). "Furthermore, we confirmed through the Gene Expression Profiling Interactive Analysis (GEPIA) database that USP14 is highly expressed in liver cancer." (PMID 38383348, 2024).
liver cancer (continued). "Furthermore, this study explored the mechanism of USP14 inhibition of liver cancer proliferation and invasion by examining its effect on the AKT and EMT signaling pathways." (PMID 38383348, 2024). "Thus, USP14 influences the growth, proliferation, and invasion of liver cancer cells, ultimately affecting the occurrence and development of liver cancer." (PMID 38383348, 2024). "Notably, this study uncovered a previously unknown connection between the USP14 and HK2 proteins, elucidating the underlying mechanism driving the development of liver cancer." (PMID 38383348, 2024). "We discovered through GEO and TCGA databases that USP14 may play an important role in liver cancer." (PMID 38383348, 2024). "However, the specific mechanism through which USP14 functions in liver cancer cells remains unclear." (PMID 38383348, 2024). "USP22, USP14, USP10, USP13, USP7, USP2, and USP8, liver cancer-related DUBs, have also been reported to have related small molecule inhibitors, but the research and development are not mature enough." (PMID 35875077, 2022). "USP14 plays a crucial role in the progression and onset of HCC — a form of liver cancer." (PMID 38383348, 2024). "Furthermore, we investigated whether sh-USP14 inhibits the AKT and SQSTM1 signaling pathways in liver cancer cells by regulating HK2." (PMID 38383348, 2024).
pancreatic cancer (5 papers, 2020 to 2025). "Elevated USP14 expression has been associated with poor prognosis in breast, colorectal, and pancreatic cancers." (PMID 40374593, 2025). "By functional CRISPR‐screening, we identified USP14, a mediator of liver metastasis of pancreatic cancer, as a key regulator of MEF2D deubiquitination and stabilization." (PMID 37828611, 2023). "Beyond the physical barrier, a recent study found that autophagy in CAFs promotes the “target loss” of CD274 through the IL6/USP14/CD274 signaling pathway, further contributing to the formation of an “immune desert” in pancreatic cancer, thereby enabling evasion from CD8+ T cell-mediated killing." (PMID 40733146, 2025). "The protein expression of WT1 was measured in pancreatic cancer cells, which were transduced with specific shRNAs for USP5, USP9x or USP14, respectively." (PMID 31845546, 2020).
cardiac hypertrophy (4 papers, 2018 to 2025). "Our studies have demonstrated that USP14 promotes cancer development and mediates progression of cardiac hypertrophy and LPS‐induced inflammation." (PMID 31970862, 2020). "USP14 promotes the progression of cardiac hypertrophy by increasing GSK-3β phosphorylation." (PMID 32471496, 2020). "In contrast to other deubiquitinating enzymes, USP14 has demonstrated to induce cardiac hypertrophy via enhancing GSK-3β phosphorylation, suggesting that USP14 can be potentially developed as a therapeutic target against cardiac hypertrophy." (PMID 30186311, 2018).
diabetic retinopathy (4 papers, 2023 to 2024). "MiR-26a-5p regulates the USP14/NF-κB pathway to alleviate inflammation and oxidative stress in diabetic retinopathy." (PMID 38699234, 2024). "For example, the lncRNA OGRU mediates diabetic retinopathy (DR) by competing for miR-320 to promote inflammation and induce the production of ROS by regulating ubiquitin-specific peptidase 14 (USP14) expression in high glucose (HG)-incubated Müller cells." (PMID 37441585, 2023). "USP1 in retinal vascular endothelial cells and USP14 in Müller cells are complicating factors for diabetic retinopathy, whereas USP28 in retinal pigment epithelial cells suppresses the progression of retinopathy." (PMID 36834633, 2023). "Collectively, these data support the idea that USP14 aggravates diabetic retinopathy by enhancing inflammation and oxidative stress." (PMID 36834633, 2023). "Additionally, the long non-coding RNA OGRU competes with miR-320 to regulate the expression of USP14, thereby mediating the progression of diabetic retinopathy." (PMID 38699234, 2024). "Additionally, miR-320 regulates USP14 expression and mediates the progression of diabetic retinopathy." (PMID 38699234, 2024).
endometrial cancer (4 papers, 2016 to 2023). Primary or metastatic malignant neoplasm involving the endometrium (mucous membrane that lines the endometrial cavity). "Pharmacological inhibition of USP14 caused dose-dependent inhibition of cell viability in endometrial cancer cell lines with an IC50 of 181.3 and 117.5 nM for HEC155 and ECC1, respectively." (PMID 27121063, 2016). "This study suggests the DUB USP14 as a promising biomarker for stratifying endometrial cancer patients at diagnosis based on their risk of recurrence." (PMID 27121063, 2016). "To this end, we first measured the expression levels of USP14 in a panel of endometrial cancer cell lines including HEC155, EFE184 and ECC1." (PMID 27121063, 2016). "This is further supported by our findings of a strong correlation between USP14 and Ki67 staining in clinical specimens of endometrial cancer." (PMID 27121063, 2016). "In light of these findings, we suggest that USP14 is a novel potential biomarker of recurrence in endometrial cancer, as well as a molecular target for its treatment." (PMID 27121063, 2016). "First, HEC155 and ECC1 endometrial cancer cells were incubated with the USP14 inhibitor VLX1570 over a period of 24 hours and the cell cycle status was analyzed by flow cytometry after staining with propidium iodide." (PMID 27121063, 2016). "Aggressive endometrial cancer cells express abnormally high levels of USP14 in situ suggesting a higher requirement for proteasome-associated DUB activity." (PMID 27121063, 2016). "Our data show a strong positive correlation between the intensity of USP14 staining and degree of proliferation as measured by Ki67 staining in clinical specimens of endometrial cancer in situ." (PMID 27121063, 2016). "Taken together this suggests a concentration-dependent anti-proliferative effect of the USP14 inhibitor VLX1570 in endometrial cancer cells at concentrations that are 500 and 800 times lower than that required for carboplatin." (PMID 27121063, 2016). "Our aim is to explore the functions and mechanism of USP14 in endometrial carcinoma (EC)." (PMID 37917013, 2023). "To date, the role of USP14 as a biomarker and molecular target in the endometrial cancer setting is largely unknown." (PMID 27121063, 2016). "Thus, we tested the hypothesis that inhibition of USP14 would result in endometrial cancer cells failing to progress through the cell cycle." (PMID 27121063, 2016). "We next wanted to investigate whether USP14 is a molecular target for endometrial cancer cells." (PMID 27121063, 2016). "Furthermore, we show that pharmacological inhibition of USP14 severely affects the viability of carboplatin resistant endometrial cancer cells with a mechanism consistent with arrest of the cells in the G2/M phase of the cell cycle followed by caspase-3 mediated onset of apoptosis." (PMID 27121063, 2016). "Further, our data showed that pharmacological inhibition of USP14 with the FDA approved inhibitor VLX1570 was accompanied by a reduction of the cell viability of endometrial cancer cells with resistance to carboplatin." (PMID 27121063, 2016).
head and neck squamous cell carcinoma (4 papers, 2023 to 2025). A squamous cell carcinoma that arises from any of the following anatomic sites: lip and oral cavity, nasal cavity, paranasal sinuses, pharynx, larynx, and salivary glands. "For example, USP14 has enhanced expression in head and neck squamous cell carcinomas and promotes TNF-α-inducible NF-κB activity." (PMID 37917013, 2023). "Additionally, USP14 inhibits the degradation of IκBα, thereby suppressing NFκB signalling and enhancing sensitivity to TNFα‐induced cell death in head and neck squamous cell carcinoma, offering a potential strategy to overcome TNFα resistance in these cancers." (PMID 40988122, 2025). "In head and neck squamous cell carcinoma (HNSCC) cells, USP14 inhibition weakened NF-κB activity." (PMID 37658402, 2023).
Hyperglycemia (4 papers, 2018 to 2024). An increased concentration of glucose in the blood. "USP14 is one of the major proteasome-associated deubiquitinating enzymes and plays a critical role in disease conditions such as hyperglycemia and heapato steatosis." (PMID 35732625, 2022). "Knockdown of USP14 expression also improved hyperglycemia, hyperinsulinemia, and insulin resistance in db/db mice." (PMID 30425250, 2018). "As a result, overexpression of USP14 promotes liver triglyceride accumulation in C57BL/6 mice, whereas genetic ablation or pharmacological inhibition of USP14 ameliorates hepatosteatosis, hyperglycemia and insulin resistance in obese mice." (PMID 30425250, 2018). "Research has shown that USP14 increases the levels and stability of 3′,5′-cyclic adenosine monophosphate response element-binding protein, enhancing the action of glucagon and hepatic glucose production, thereby promoting hyperglycemia." (PMID 38699234, 2024).